TLR7 (toll like receptor 7)
Diseases named in the same sentence as TLR7 in open-access papers (continued):
Sharing a sentence is not in itself a finding about the gene and the disease.
Autoimmunity (continued). "ABC identified in models of autoimmunity are dependent on BcR, TLR-7, and TLR-9 stimulation, and memory ABC populations are implicated in mediating autoimmunity." (PMID 29632538, 2018). "Evidently, TLR9 and TLR8 inhibit TLR7-mediated autoimmunity and renal inflammation in a synergistic manner." (PMID 29650017, 2018). "In fact, the implication of TLR9 activation in mouse models has complex consequences as TLR9 on B cells restrains TLR7-mediated spontaneous autoimmunity in C57BL/6 mice." (PMID 28970832, 2017). "In Yaa mouse models, duplication of the Tlr7 gene was reported to be the sole requirement for accelerated autoimmunity and that reduction of Tlr7 gene dosage abolished the autoimmune phenotype." (PMID 28456914, 2017). "It has been shown in mouse models that BANK1 regulates TLR7 signaling in B-cells and that B-cell innate immune response via TLR7 is critical for the development of autoimmunity." (PMID 27933432, 2017). "Of note, overexpression of soluble RNAase ameliorated autoimmunity in TLR7-transgenic mice suggesting an important role for RNA in the pathogenesis of disease in these mice." (PMID 28456914, 2017). "Stimulation of TLR7 in conjunction with CD40 activation of DCs can induce diabetogenic CTLs in the pancreatic lymph nodes of NOD mice to promote onset of autoimmunity." (PMID 29018409, 2017). "Paradoxically, TLR9 also plays known protective roles against autoimmunity by directly and indirectly inhibiting TLR7-mediated autoantibody production." (PMID 28751890, 2017). "The opposite, pro-inflammatory vs. regulatory, effects are consistent with the dual role of TLR7/8 agonists in driving either protective immunity or chronic inflammation/autoimmunity." (PMID 29312324, 2017). "Here we show a critical role of pDCs in TLR7-mediated autoimmunity using gene-modified mice with impaired expression of Siglec-H and selective ablation of pDCs." (PMID 27075414, 2016). "Introducing the Tlr7-bearing yaa gene segment to B6.Sle1 mice also accelerated autoimmunity, in which the disease severity positively correlated with the Tlr7 expression level." (PMID 27509492, 2016). "Involvement of MicroRNA-29b-containing exosome was implicated in regulating innate and antigen-specific immune response in mouse model of autoimmunity via TLR7 signaling." (PMID 26954233, 2016). "During TLR7-mediated autoimmunity, when produced by B cells, type I interferon is taken up by IFNAR leading to the transcription of more interferon generating a positive feedback loop." (PMID 27228057, 2016). "Further researches are needed to strengthen the role of TLR-7 on these cells as a mechanism of action in autoimmunity." (PMID 26870038, 2016). "In fact, several studies have found that polymorphisms in viral RNA sensors such as Toll-like receptor 7 and MDA-5, also result in autoimmunity." (PMID 25951191, 2015). "Considering the importance of TLR7 activation in autoimmunity, IL-7 should be considered a future candidate for intervention studies." (PMID 26137972, 2015). "Opposing effects were described for TLR7 and TLR9: deletion of TLR7 limited autoimmunity, whereas TLR9 deletion paradoxically exacerbated disease." (PMID 26137972, 2015). "Increased Tlr7 gene dosage promotes autoreactive lymphocytes activation, dendritic cells proliferation, and secretion of proinflammatory cytokines and IFN-α, which in turn upregulates TLR7 expression, leading to a feedback loop exacerbating autoimmunity." (PMID 23468661, 2013). "In summary, TLR7-modified immunoregulation by Tregs contributes to the breakdown of peripheral tolerance and development of autoimmunity in SLE, where activation of TLR7 by endogenous ligands was shown to play a role in the pathogenesis." (PMID 21860649, 2012). "TLR7 overexpressing transgenic mice have demonstrated that duplication of the TLR7 gene is the sole requirement for this accelerated autoimmunity, as reduction of TLR7 gene dosage abolishes the Yaa phenotype." (PMID 22761632, 2012).
Autoimmunity (continued). "Excess TLR activation as seen in Yaa mice with TLR7 duplication or TLR7 transgenic mice also leads to autoimmunity." (PMID 20625435, 2010). "TLR-7 promotes disruption of GC tolerance and stimulates extrafollicular B-cell activity, contributing to autoimmunity, whereas TLR-9 has a dual role, suppressing immune activation under normal conditions but promoting anti-nuclear antibody (ANA) production in autoimmune contexts." (PMID 41283475, 2025). "Additionally, UNC93B1 variants have been linked to TLR7‐dependent autoimmunity, and the instability of the UNC93B1 protein decreases contact with TLR7 but overactivates specific TLR7 with a continuous type I IFN response in macrophages." (PMID 40491969, 2025). "Preclinical data suggest that TLR3 agonism—e.g., poly(I:C)—may be protective, whereas TLR7/8/9 activation enhances remodeling and autoimmunity." (PMID 41303627, 2025). "Incidentally, the X chromosome has a high density of genes involved in immune functions, and some of these, including TLR7, TASL, CXCR3, or CD40LG, tend to be overexpressed in autoimmune conditions, suggesting a causal link between autoimmunity and X-linked gene regulation." (PMID 38701219, 2024). "An increase in TLR7 exacerbates autoimmunity and nephritis in mice." (PMID 38772735, 2024). "Expression of two copies of Tlr7 in male mice is sufficient to induce full-blown autoimmunity." (PMID 38701219, 2024). "As a control, we also generated THP-1 cells expressing hUNC93B1 with amino acids 530–532 (Pro, Arg, Pro) mutated to alanine (hUNC93B1PRP/AAA), which corresponds to the mutation in the C-terminal tail of mice that we previously showed leads to TLR7-driven autoimmunity." (PMID 38780621, 2024). "The ability of B cells to produce autocrine BAFF and sustain their own survival could play an important role in Type-I IFN and TLR7-driven autoimmunity." (PMID 36923413, 2023). "The conventional dendritic cell expression of TLR7 is essential for severe autoimmunity in SLE." (PMID 37894915, 2023). "Therefore, neutrophils seem to play an important role in regulating inflammation and autoimmunity through TLR7/8 activation and in influencing other immune cell effector functions." (PMID 36359340, 2022). "mtDNA interacts with and activates a wide variety of immunostimulatory DNA sensors, such as cyclic guanosine monophosphate-adenosine monophosphate synthase (cGAS) and Toll-like receptors (TLR7/9), which can induce autoimmunity, activating type I interferon inflammatory responses." (PMID 36430958, 2022). "Besides, antagonism between TLR7 and TLR9 in B cell was well demonstrated in both in vivo and in vitro studies, in which TLR9 plays protective roles against autoimmunity through inhibiting TLR7-mediated autoantibody production." (PMID 35345674, 2022). "Overriding this checkpoint promotes TLR7 activation, triggers spontaneous GC responses in the absence of exogenous antigen, and accelerates the onset of autoimmunity-linked phenotypes in MRL-LPR mice." (PMID 35653193, 2022). "There, mtDNA interacts with and activates a variety of immunostimulatory DNA sensors, including cyclic guanosine monophosphate-adenosine monophosphate synthase (cGAS) and Toll-like receptors (TLR7/9), which can trigger autoimmunity by activating IFN-α inflammatory responses." (PMID 36430958, 2022). "For example, EBV infection could affect TLR7/9-dependent innate immune responses, which enhance the inflammatory response, B-cell dysfunction, and autoimmunity in the thymus of patients with MG." (PMID 35795289, 2022). "Therefore, both TLR8 and TLR9 are able to restrain TLR7 and their deletion leads to autoimmunity due to increased TLR7 responses." (PMID 36389822, 2022). "Eventually, syntenin-1 may play a role in the dynamic regulation of TLR7, which is involved in self-RNA recognition, and therefore autoimmunity." (PMID 34576267, 2021). "TLR7 is an intracellular Toll-like receptor that is known for its importance in autoimmunity." (PMID 33596908, 2021).
Autoimmunity (continued). "Increased TLR7 activity promotes autoimmunity, and there are indications that partial escape of TLR7 from X-chromosome inactivation may contribute to the extreme sex-bias in SLE incidence." (PMID 34440442, 2021). "TLR-7 activation increased type I IFN secretion in the blood increasing autoimmunity." (PMID 34444829, 2021). "Gene-edited mice expressing a mutant Unc93B1 in which three critical amino acids of this C-terminal domain were altered (530-PKP/AAA-532) developed hallmarks of systemic inflammation and autoimmunity, similar to what has been observed in Tlr7 overexpressing mice." (PMID 32028618, 2020). "TLR3 appears to exist as a functional receptor on the cell membrane more frequently than other endosomal TLRs, probably because endogenous agonists of TLR7, TLR8, and TLR9 are more abundant than dsRNA in uninfected cells, and therefore surface localization of TLR3 poses a lower risk of autoimmunity." (PMID 33597952, 2020). "Thus, the pathogenic roles of TLR7 and type I IFN signaling in lacrimal gland autoimmunity in NOD mice are complex." (PMID 33322152, 2020). "Finally, B cell intrinsic deletion of IFNγR was sufficient to restore B10 cells in the spleens of TLR7-promoted autoimmune mouse model." (PMID 32849556, 2020). "Although we found that topical TLR7 stimulation caused mild autoimmunity in WT B6 mice as evidenced by low +ANA, no significant nephritis was observed on histology or functional studies (24 h albuminuria), despite high animal mortality." (PMID 31998321, 2019). "In other model systems, a higher copy of TLR7 permits the progression to severe autoimmunity in the absence of any additional susceptibility locus." (PMID 31354711, 2019). "In addition, abolishing the function of plasmacytoid dendritic cells in TLR7.Tg mice, a model of TLR7-driven autoimmunity, attenuated glomerular immune complex deposits and prolonged lifespan of the mice." (PMID 29650017, 2018). "Genetic factors affecting CD22 or TLR7 expression may affect the ability of CD22 to regulate TLR7-mediated B cell activation and contribute to autoimmunity." (PMID 30323814, 2018). "TLR7 overexpression in B6.yaa mice illustrates that increased TLR7 activity alone is not sufficient to trigger autoimmunity without gene variants in other susceptibility genes." (PMID 29650017, 2018). "Additionally, autoimmunity in TLR7[Tg] animals is dependent on CD40-CD40L signaling as Tlr7 overexpressing animals deficient in CD40L are completely protected from systemic disease." (PMID 28098193, 2017). "That controlling TLR7 expression is essential in restricting autoimmunity already became clear when TLR7 gene duplication was demonstrated to be the sole requirement for accelerated autoimmunity in B6.Yaa mice." (PMID 26137972, 2015). "Absence of TLR7 partially ameliorates disease whereas deficiency of TLR9 exacerbates autoimmunity in a TLR7-dependent manner." (PMID 23557436, 2013). "Moreover, S100A8/9 contributed to TLR7-mediated autoimmunity." (PMID 38429401, 2024). "Hence, the link between Tlr7 overexpression and autoimmunity has been firmly established." (PMID 38701219, 2024). "Therefore, we detected apoptosis in myocardial tissue; (c) Olivia Majer et al46 reported that immune cells release TLR7 into exosomes to suppress autoimmunity, an indication that TLR7 is transported from the immune cells into cardiomyocytes by releasing TLR7 into exosomes." (PMID 33463061, 2021). "To investigate whether increases in plasma TMAO concentrations contribute to autoimmunity and high BP in TLR7-dependent systemic autoimmunity, we fed mice a normal chow diet for 8 weeks with their drinking water either supplemented with DMB or not supplemented." (PMID 35052589, 2021). "Aberrant TLR7 activation may play an important role in the pathogenesis of autoimmunity." (PMID 30610201, 2020). "Besides affecting humoral immune responses, TLR7 also influences T cell responses in autoimmunity." (PMID 33297945, 2020).
Autoimmunity (continued). "However, our data points to a TLR7-independent role of MAVS in the development of autoimmunity." (PMID 31681326, 2019). "In addition increased Tlr7 gene dosage promotes dendritic cell proliferation and cytokine secretion, further upregulating Tlr7 expression and serving as a positive feedback loop exacerbating autoimmunity." (PMID 26717913, 2015). "Human and mouse studies strongly support the involvement of both the endosomal TLR7 and TLR9 (TLR7/9) pathways and IRF5 in the pathogenesis of SLE and related autoimmune conditions such as psoriasis and Sjögren’s disease." (PMID 39856058, 2025). "In contrast, testosterone downregulates TLR7 expression and dampens IFN-I responses, providing a protective effect against autoimmunity in males." (PMID 40806232, 2025). "Upon ligand binding, TLR7 and TLR9 recruit the adaptor MyD88, which initiates a signaling cascade leading to IRF5 activation, which is critical to trigger autoimmunity." (PMID 41178711, 2025). "In pDCs and myeloid DCs, TLR7 drives IFN-I and cytokine production, and chemokine migration to inflammatory sites, promoting autoimmunity and tissue damage." (PMID 40806232, 2025). "It is striking that all single-stranded endosomal RNA sensors (i.e., TLR7, TLR8, and TLR13) are codified in the X chromosome, possibly explaining sex-biased autoimmunity due to defects in dosage compensation." (PMID 40334662, 2025). "Another study focused on TLR7/8 showed that topical application of the TLR7/8 agonist resiquimod (R848) in SU5416 rats exhibited severe symptoms of PH and autoimmune disorders, implicating the immunopathological link of autoimmune vasculopathy." (PMID 39125996, 2024). "Uncontrolled TLR7, TLR8, or TLR9 activation can lead to responses to self-nucleic acids and autoimmunity." (PMID 38780621, 2024). "The IFN-I elicited by LAIV can be attributed to TLR7 signalling, and whilst IFN-I is a powerful vaccine adjuvant, excessive induction leads to hyperinflammation and autoimmunity." (PMID 38481993, 2024). "Intracellular TLRs recognise bacterial and viral nucleic acids and self-nucleic acids in autoimmunity; these include TLR3, TLR7, TLR8, TLR11, and TLR12." (PMID 37761018, 2023). "A similar correlation between up-regulation of TLR7 and high BAFF serum levels occurs in immune thrombocytopenia, another autoimmune disorder." (PMID 36923413, 2023). "Excess TLR7 or TLR8 activity, by contrast, can lead to sterile inflammation and autoimmunity, and is an important contributor to the pathogenesis of autoimmune syndromes." (PMID 37723501, 2023). "However, TLR7 hyperactivity may also drive the initiation and progression of autoimmunity." (PMID 37894915, 2023). "We will briefly introduce nucleic acid TLRs and present data for the interplay of TLR7 with TLR8 and TLR9 and its importance in autoimmunity." (PMID 36389822, 2022). "Nevertheless, by now it is undoubtedly documented that TLR7 plays a central role in SLE, where both TLR8 and TLR9 restrain TLR7 signaling and thus, can protect from autoimmunity." (PMID 36389822, 2022). "The functional interaction between TLR7 and TLR9 within B cells is important for B-cell dysregulation in autoimmunity." (PMID 36220996, 2022). "AIM-100, an inhibitor of ACK1, can significantly inhibit TLR4/TLR7/TLR9-induced activation of macrophages and DCs and alleviates the TLRs-mediated inflammation and autoimmunity." (PMID 35669783, 2022). "TLR7 is an endosomal TLR that recognizes single-stranded RNA (ssRNA) and mediates the development of inflammation and autoimmunity." (PMID 34692568, 2021). "In this work, the authors elucidated a role for Gal9 in restraining TLR7 and TLR9 responses in pDCs, important drivers of type I IFNs and the inflammatory profile that supports autoimmunity." (PMID 34369876, 2021). "When excessive cellular or tissue damage occurs, the activation of TLR7 or TLR9 by endogenous nucleic acids can be exacerbated, leading to autoimmunity phenomena." (PMID 34458163, 2021).
Autoimmunity (continued). "Pharmaceutical inhibition of PKM2 by PKM2-IN can inhibit TLR4/TLR7/TLR9-induced activations of macrophages, DCs and B cells, and alleviate the pathogenesis of TLRs-mediated inflammation and autoimmunity." (PMID 34025679, 2021). "To evaluate the role of TLR7 in the development of autoimmunity in NOD mice, we developed Tlr7 knockout (KO) NOD mice through CRISPR/Cas9-mediated gene editing directly in NOD mouse embryos resulting in a 2 base-pair deletion in Tlr7." (PMID 33322152, 2020). "Although TLR7 and TLR9 are similar in structure and involved in autoimmunity by recognizing self-RNA and self-DNA, respectively, contradictory actions for autoimmune disease models are observed." (PMID 33371432, 2020). "Our study thereby links all three observations, enhanced TLR7 and −9 responses, increased type I IFN gene expression and autoantibodies, further highlighting their importance in autoimmunity." (PMID 30846988, 2019). "In the host body, particular caution is required in activating nucleic-acid-sensing TLRs, such as TLR3, TLR7, and TLR9, to avoid self-recognition and thus the induction of autoimmunity." (PMID 31892731, 2019). "Since expression in Sle1Tg7 is higher than the respective Sle1Tg7IRAKKD/KD mice, it confirms that the inflammatory environment of severe autoimmunity and signaling through IRAK4 contributes to the increase in TLR7 expression." (PMID 31354711, 2019). "The role of TLR7 and TLR8 in promoting autoimmunity has also been indicated in CVB3-induced self-reactivity toward myocardial tissue." (PMID 29018409, 2017). "Since immune dysregulation and autoimmunity was largely confined to the B cell compartment, results suggest that the TLR9 and TLR7 effects were B-cell intrinsic." (PMID 28751890, 2017). "TLR7/TLR9 responses have substantiated roles in both autoantibody production and autoimmunity, especially in B cell receptor (BCR)-activated B cells." (PMID 28751890, 2017). "Endosomal toll-like receptors (TLRs), such as TLR7 and TLR9, are key mediators of autoimmunity." (PMID 42112403, 2026). "These experiments lacked TLR7 dosage controls, despite TLR7 gene dosage being a well established driver of autoimmunity." (PMID 41178711, 2025). "TLR7 agonists, but not TLR3, TLR4 or TLR9 agonists, induce the accumulation of atypical memory CD11c+ B cells (ABCs), associated with autoimmunity." (PMID 38571942, 2024). "This suggests that previously intact TLR7 and TLR9 signaling may have contributed to the development of autoimmunity." (PMID 37626865, 2023). "Taken together, these results confirmed our hypothesis that ACK1 promotes TLR4/TLR7/TLR9-induced activation of macrophages and DCs, therefore contributes to the pathogenesis of TLR-mediated inflammation and autoimmunity." (PMID 35669783, 2022). "Thus, as soon as it was discovered that TLR7 and TLR9 detect viral and bacterial nucleic acids, various studies deployed to evaluate their role in autoimmunity, predominately by studying experimental mouse models." (PMID 36389822, 2022). "Aberrant activation of STAT3 due to a gain of functionality might lead to an imbalance of TLR7 and TLR9 response through accelerating integrin signaling pathway, further affecting the development of autoimmunity." (PMID 35345674, 2022). "The autoimmunity and glomerulonephritis observed in NZBWF1 mice are partially TLR7-mediated, but whether the hyperinsulinemia and impaired glucose tolerance are also related to TLR7 activation has not been studied to our knowledge." (PMID 35874527, 2022). "For example, RNF115 negatively regulates TLRs-mediated signaling and autoimmunity and targeting RNF115 might promote TLR4-related sepsis or TLR7/9-related autoimmunity." (PMID 35844553, 2022). "Phosphorylation of Stat1 at S727 is similarly required in B cells for autoimmunity in the Sle1b + TLR7 model, but not for responses to foreign antigens." (PMID 33519824, 2020).